RAC1 (Rac family small GTPase 1)
Diseases named in the same sentence as RAC1 in open-access papers (continued):
Sharing a sentence is not in itself a finding about the gene and the disease.
cancer (continued). "In conclusion, six core genes including COL3A1, EEF2, FN1, PTPRF SDC2, and RAC1, and several cancer-related metabolic processes, signaling pathways, and overall survival rate of patients were identified in BM PCa." (PMID 34229299, 2021). "Inhibition of β2-chimaerin protein mediated by hippocampus effector TAZ leads to the persistence of Rac1 activity in cancer stem cells (CSCs)." (PMID 34079763, 2021). "While none of the inhibitors targeting these GTPases have been approved for cancer therapy to date, RAC1/Cdc42 inhibition as a strategy to overcome therapy resistance has been validated previously." (PMID 33603169, 2021). "Rac1 protein, which belongs to the Rho family of GTPases, is involved in the tumorigenic and migratory phenotypes of cancer cells." (PMID 33668218, 2021). "PARD3 directly activates Rac1, promoting proliferation and motility of cancer cells, and leads to tumorigenesis, angiogenesis, invasion and metastasis." (PMID 34040099, 2021). "Collectively, we conclude that the Golgi apparatus pathways, instead of the Rac1/Cdc42 signaling pathway, are likely to play a more effective role in regulating the collective polarization of carcinoma cells." (PMID 33499191, 2021). "Targeting Rictor, as well as its downstream molecule Rac1, suppresses IDH1-mutated cancer progression with reduced cell motility and endocytosis." (PMID 32224866, 2020). "EHop-016 was identified during the optimization of NSC23766, and suppresses cancer cell migration through interfering with the binding of Rac1 to Vav2." (PMID 32392742, 2020). "Due to this, the potential role of RhoA and Rac1 in tumour development has attracted a great deal of attention from the research community in cancer biology." (PMID 32731493, 2020). "Using different cancer models, we have already validated Rac1 as a target and 1A-116 as a small molecule to be potentially exploited in therapeutics schemes." (PMID 32351958, 2020). "Dysregulation of the Rac1 signaling pathway, resulting in elevated motile and invasive potential, has been reported in multiple cancers." (PMID 32092966, 2020). "Small Rho GTPases including RhoA, Rac1, and Cdc42 are well known to regulate cell migration, and overexpression of these molecules in human cancer correlates with cancer progression." (PMID 32802134, 2020). "Rho GTPases (RhoA, Rac1, and Cdc42) have been studied in connection with breast carcinogenesis, as well as in connection with other cancers, for many years." (PMID 32443784, 2020). "Using a rational design approach, our group has developed 1A-116 as a promising Rac1 inhibitor, with antitumoral and antimetastatic effects in several types of cancer." (PMID 32351958, 2020). "The small GTPases Rac1 and Cdc42 have been recognized as major players in cancer progression and perform essential roles in metastasis." (PMID 32092966, 2020). "This has been shown in a great variety of tumor types and gives the basis to consider Rac1 as an attractive and validated target to develop molecular therapies against cancer metastasis." (PMID 32351958, 2020). "Our discovery of the pivotal role of Rac1 in enhancing nucleotide metabolism and inducing chemoresistance in multiple human cancers makes Rac1 as an attractive therapeutic target for potent sensitization to DNA damaging chemotherapies." (PMID 32193458, 2020). "Together with our studies, the potential contribution of Rac1 to the resistance to anti-cancer chemotherapeutic drugs, highlights the critical need to develop treatment strategies to target Rac1 related pathways in a clinical setting." (PMID 32193458, 2020). "This Hippo-pathway effector protein led to the inhibition of cancer cell autophagy-related cell death through the intermediary signaling of the RAC1/ROS/ (mammalian target of rapamycin) mTOR pathway." (PMID 32545340, 2020).
cancer (continued). "Rac1 has been consistently involved in the activation of pro-survival pathways in cancer cells, such as NF-κB, thereby counterbalancing the apoptotic responses triggered by chemotherapeutic agents and radiation therapy." (PMID 32158759, 2020). "Recent studies have shown that Rac1 activation promotes cancer progression via the PAK/RAF/ERK pathway." (PMID 32193458, 2020). "The spatio-temporal effects of RAC1 are especially important in cancer tissue’s response to cellular stress, specific DNA damage, and the DDR." (PMID 32545340, 2020). "The pro-proliferative function of activated RAC1 by virtue of which it contributes to cancer progression and therapy resistance involves stress response proteins, including NF-κB, JNK, and p38." (PMID 32545340, 2020). "Although we recorded Rac1-guided cellular motility in IDH1-mutated cells, a key question remains elusive with regards to how Rac1 is regulated in this type of cancer." (PMID 32224866, 2020). "Apart from its function as a caspase inhibitor, XIAP in cancer cells inhibits cell adhesion, migration, and motility by controlling Rho GTPase proteins, such as Rac1 and Cdc428–13." (PMID 32994395, 2020). "The results reported here suggest differential regulation of CTD phosphatases by Cdc42 and Rac1 in human cancer cell culture." (PMID 32143485, 2020). "Several proteins have been cited as pro-angiogenic factors in the progression of cancer, including RAC1, MMPs, TIMP, and Nck1." (PMID 32545340, 2020). "There have been several excellent studies for exploring the therapeutic potentials of various natural products for their role in inhibiting cancer cells migration and function via regulating the Rac1/2 and Cdc42." (PMID 32578854, 2020). "This would be very important for reducing the influences of Rac1 on cellular functions of cancer cells to reverse chemoresistance and improve therapeutic efficacy." (PMID 33604328, 2020). "PI3K–Akt signaling is reported to be involved in cancer cell invasion by modulating NF-κB-mediated MMP-2 expression through the control of Rac1 activity." (PMID 32033487, 2020). "When Rac1 is activated, it launches a broad spectrum of downstream pathways and involves in modulating various processes of cancer progression, including cytoskeletal reorganization, migration, invasion and metastasis." (PMID 33604328, 2020). "These processes are tightly regulated by Rac1, a small G-protein that participates in the formation of actin-rich membrane protrusions required for cancer cell motility and for the secretion of extracellular matrix (ECM)-degrading proteases." (PMID 32158759, 2020). "In particular, the small G-protein Rac1 plays a key role in the formation of actin-rich projections, such as lamellipodia and ruffles required for cancer cell motility, and invadopodia which leads to ECM degradation through the deposition of proteases." (PMID 32158759, 2020). "We provided pharmacological and genetic evidence showing a similar Pol II CTD code modulation by Cdc42 and Rac1 GTPases in cultured human cancer cells." (PMID 32143485, 2020). "Low doses of berberine derived from Coptidis rhizome inhibited Rho GTPase including RhoA, Cdc42, and Rac1 and cell migration in different human cancer cells." (PMID 32443784, 2020). "It has also been shown that increased Rac1 activation promotes cancer cell proliferation, migration, and metastasis." (PMID 32585958, 2020). "Rac1 GTPase is required for cell migration and its hyperactivation results in cancer invasiveness and progression." (PMID 32814766, 2020). "Upregulated upstream effectors of RAC1 are a frequent mechanism in which cancer cells obtain an invasive, migratory phenotype." (PMID 32545340, 2020). "Rac1-regulated NF-κB transcriptional activity is required for MMP-2/-9-driven invasion of cancer cells." (PMID 32823607, 2020).
cancer (continued). "Our results suggest that Rac1 and Cdc42 GTPase signaling in cultured human cancer cells similarly modulates the CTD Ser2 and Ser5 phosphorylation status." (PMID 32143485, 2020). "The invasive phenotype of metastatic cancer cells causes the remodelation of extracellular matrix by producing metalloproteases, key components of the EMT also regulated by Rac1." (PMID 32351958, 2020). "DDR, a complex cellular signaling algorithm involving cell cycle checkpoints, DNA repair, and apoptosis, is thought to be a cell’s response to genotoxic stress and is essential for the anti-apoptotic function of RAC1-overexpressed cancer cells." (PMID 32545340, 2020). "Several studies indicated that the activity of Vav1 as a GEF towards Rac1 plays an important role in Vav1’s involvement in cancer." (PMID 32277014, 2020). "Since the activation of Rac1 is regulated by GEFs, targeting Rac1-GEF complex is taken advantage to develop cancer therapeutics." (PMID 33604328, 2020). "The most studied Rho GTPases in oncogynecology are RhoA, RhoC, Rac1, and Cdc42, which show higher expression correlating with the advancement of the cancer." (PMID 32443784, 2020). "In cancer cells, p120catenin has also been reported to activate Rac1, which, in combination with reduced substrate adhesion due to RhoA inhibition, promotes cancer cell invasion." (PMID 32443411, 2020). "Our review focuses on the role of RAC1 in adult solid-tumors and summarizes the contextual mechanisms of RAC1 involvement in the development of resistance to cancer therapies." (PMID 32545340, 2020). "Several chemical compound were developed for targeting Rac1 and showed anti-cancer effects in cell lines or animal models." (PMID 32193458, 2020). "Cancer cell invasion plasticity is known to be controlled by shifting the balance in the mutually antagonistic regulation of Rac1 and RhoA." (PMID 32872349, 2020). "As a first step, we chose to study DOCK4 and DOCK9 among a large family of GEFs, given that DOCK4 and DOCK9 have been demonstrated to respectively activate Rac1 and Cdc42 and that mutations in DOCK4 and DOCK9/Zizimin1 have been found in a number of cancers." (PMID 32143485, 2020). "In this context, the regulatory activity of Rac1 affects several key processes in the course of the cancer including invasion and metastasis." (PMID 32351958, 2020). "The RAC1 GTPase is a ubiquitously expressed member of the renowned Rho family of GTPases important across many cell-signaling processes relevant to cancer." (PMID 32545340, 2020). "Recent works report that Rac1 plays a very important role in cancer cell proliferation and survival." (PMID 32585958, 2020). "IQGAP1 stimulates filopodia formation, and promotes cell motility and invasion in mammalian and cancer cells, particularly through the interaction with β-catenin, e-cadherin, and small GTPase, i.e., Cdc42, Rac1, and RhoC." (PMID 32824461, 2020). "The GTPase Rac1 is a well-established master regulator of cell motility and invasiveness contributing to cancer metastasis." (PMID 32092966, 2020). "In this review, we attempt to summarize the multiple layers how calmodulin can regulate KRas and Rac1 GTPases in a variety of cellular events, with biological consequences and potential for therapeutic opportunities in disease settings, such as cancer." (PMID 32456244, 2020). "Our findings on the inhibitory effects of ropivacaine on Rac1 activity is consistent with the previous report that ropivacaine inhibits Rac1/JNK/paxillin in cancer cells." (PMID 32450791, 2020). "Previous studies indicate that the involvement of RAC1 in regulating chemoresistance differs in various types of cancers." (PMID 31314174, 2019). "Recently, it was reported that loss of miR-204 resulted in BDNF/TrkB overexpression and activation of the AKT/mTOR/Rac1 signaling pathway in cancer cells." (PMID 31480771, 2019).
cancer (continued). "Our attention was drawn to the large number of regulators of Rho-family GTPases such as Rac1, Rho, and Cdc42, known to be involved in the regulation of cell motility, and considered as interesting drug targets to prevent cancer dissemination." (PMID 30971775, 2019). "Rac1 plays an important role in cancer progression, affecting cell adhesion, proliferation, migration, invasion, and cancer metastasis." (PMID 31338333, 2019). "Loss of Pard3 has been shown to promote tumorigenesis in different human cancers via Tiam1/Rac1-dependent mechanisms." (PMID 30171257, 2019). "In EOC, cytoplasmic p120ctn regulates the activation of the Rho GTPases RhoA, Rac1 and Cdc42, which are known to be essential modulators for cell migration and invasion and consequently promoting cancer cell motility and invasion." (PMID 30795761, 2019). "Their activation also tightly depended on the mammalian target of rapamycin (mTOR) activation, which indicated that mTOR can be critical in regulating cancer metabolism on the downstream of RAC1." (PMID 31314174, 2019). "RAC1 controls cancer cell invasion by regulating the production of matrix metalloproteinases, MMPs (RAC1/PAK1/p38/MMP-2 axis regulated angiogenesis), and their natural inhibitors, the tissue-specific inhibitors of MMP (TIMPs)." (PMID 31027363, 2019). "Cytoplasmic p120ctn was found to interact with Rho GTPases RhoA, Rac1 and Cdc42 to influence cancer cell motility and metastasis." (PMID 30795761, 2019). "Recent studies have shown that NEDD9 is involved in the control of cancer cell mesenchymal-mode movement in three-dimensional environments by affecting the Rac1 signaling cascade." (PMID 31462898, 2019). "We have presented patterns of distribution of the frequency of RAC1-alteration(s) in cancers as obtained from cBioPortal." (PMID 31027363, 2019). "This analysis demonstrated that RAC1-dependent cancer cells are particularly sensitive to depletion of WAVE complex subunits, ARP2/3 subunits, and focal adhesion components." (PMID 31257073, 2019). "We showed that ΔNp63α downregulates PKCγ expression and Rac1 phosphorylation through miR-320a, thus suggesting a potentially novel mechanistic link between p63 and cancer invasiveness through the regulation of the Rac1 small GTPase." (PMID 31515469, 2019). "Upregulation of NEDD9 is reported to activate Rac1 GTPase and drive mesenchymal-mode movement of cancer cells." (PMID 31019460, 2019). "Taken together, our data suggest that ΔNp63α positively regulates miR-320a, thereby inhibiting PKCγ expression, Rac1 phosphorylation, and cancer invasion." (PMID 31515469, 2019). "We have recently demonstrated that the upregulation of EMP1 expression facilitates cancer cell migration and invasion through the activation of a small GTPase, Rac1." (PMID 31652725, 2019). "Previous reports showed that cancer cells that carry mutations in RAS and Rac1 genes are more sensitive to PAK inhibitors." (PMID 30971268, 2019). "All together, the studies conducted on the coordination of Rac1 and Rab proteins in several processes occurring during cancer development, progression, and metastasis show how interconnected the roles of these proteins are." (PMID 31035701, 2019). "Rac1 and Rab proteins’ coordination has been proven to be important for mechanisms involved in cancer, neurological diseases, and infections." (PMID 31035701, 2019). "Blockade of Rac1 activity with the NSC compound or overexpression of Rac1-DN was detrimental to HPV positive cancer cell proliferation and resulted in approximately 50% fewer colonies than the controls." (PMID 31226168, 2019). "Our review focuses on the role of RAC1 in cancers and summarizes the regulatory mechanisms, inhibitory efficacy, and the anticancer potential of RAC1-PAK targeting agents." (PMID 31027363, 2019).
cancer (continued). "Specifically, we found that inhibiting protein SUMOylation induces autophagic cell death through the upregulation of the pseudokinase TRIB3, and it impairs cancer cell invasiveness by inhibiting activation of the small GTPase RAC1." (PMID 31578236, 2019). "The presence of a long-tail and absence of alteration of RAC1 in more than half of the cancer types is the characteristic feature of alterations of the RAC1 gene in cancers." (PMID 31027363, 2019). "The current study revealed that the differential role of KRT19 in different cancers is due to interactions with either β-catenin alone or with the β-catenin/RAC1 complex, and consequent stabilization and nuclear import of the molecular complex." (PMID 30650643, 2019). "In the future, it is expected that the scientific knowledge will be put into action in clinics towards designing personalized clinical trials for the therapeutic management of cancers in which a specific involvement of RAC1 has been identified." (PMID 31027363, 2019). "The new study highlights the importance of Rac1 activation in cancer metastasis and acquired chemoresistance." (PMID 31338333, 2019). "Rac1 activity and expression are frequently elevated in tumors and a recent meta-analysis of 1,793 patients in 14 studies concluded that Rac1 expression was a poor prognostic indicator across cancers." (PMID 31344967, 2019). "Collectively, these results indicate that inhibition of TIAM1 suppresses cancer stemness in part through inhibition of Rac1 phosphorylation." (PMID 30890693, 2019). "A recent study on human carcinoma cell showed that EIPA can block the activation of the Rac1 and Cdc42 signaling pathways by lowering submembranous pH, therefore, macropinocytosis pathway was inhibited." (PMID 31449523, 2019). "The in vivo and in vitro studies in the last decades have firmly established the role of Rac1 in cancer cell invasion and metastasis." (PMID 30544910, 2018). "We found that the NMac1 binding on C-terminal region of Nm23-H1 causes allosteric regulation of nucleotide binding and activates the NDPK activity and that NMac1 significantly reduces cell invasion in vitro via Rac1 inhibition and cancer metastasis in vivo." (PMID 30026594, 2018). "Hepatocyte growth factor (HGF) induces a MET-AXL-ELMO2-DOCK180 complex that activates Rac1-dependent cancer cell migration and invasion." (PMID 30261690, 2018). "In cancer, Rac1 is frequently released from normal control mechanisms through mutation, aberrant regulation of nucleotide binding and hydrolysis, and altered splicing." (PMID 30261690, 2018). "Small G protein Rac1 is the chief member of Rho family which play important role in regulating migration of cancer cells." (PMID 29510732, 2018). "Overexpression of Rac1 leads to increased growth of human CRC cells, whereas downregulation of Rac1 expression by siRNA interferes with cancer progression." (PMID 29796160, 2018). "Overexpression of miR-124 suppresses migration, cell proliferation, and invasion and induces apoptosis by regulating Rac1, indicating that miR-124 plays a tumor suppressive role in various cancer." (PMID 30062087, 2018). "Rac1 as a direct target of miR-124, it has a fundamental role in tumorigenesis and invasion of cancer cells." (PMID 30062087, 2018). "In humans, Rac1 expression correlated with blood vessel invasion in a meta-analysis of multiple cancer studies." (PMID 30261690, 2018). "RAC1 has previously been linked to PI3K/AKT/MTOR and RAF/MEK/ERK signalling and both these pathways can be important mechanisms of cancer cell evasion of apoptosis." (PMID 29329780, 2018). "We conclude that oncogenic RAC1 and NRAS mutations protect cancer cells from ER-stress by activating ERK1/2." (PMID 29329780, 2018). "After 72 hours of incubation with AIIB2, Rac1 protein levels decreased in both cancer cell lines and primary tumor cells, indicating that AIIB2-induced inhibition of β1 integrin downregulates Rac1." (PMID 29435106, 2018).